PM20D2 (peptidase M20 domain containing 2)
Description:
Catalyzes the peptide bond hydrolysis in dipeptides having basic amino acids lysine, ornithine or arginine at C-terminus. Postulated to function in a metabolite repair mechanism by eliminating alternate dipeptide by-products formed during carnosine synthesis.
Synonyms: ACY1L2; bA63L7.3
Tractability: PROTAC: ubiquitination databases record sites on it; its protein half-life has been measured.
Target class: Enzyme; Hydrolase
Gene: Protein-coding gene on chromosome 6 (89,146,055 to 89,165,565, forward strand). Ensembl gene ENSG00000146281.
Subcellular location (Human Protein Atlas): Nucleoplasm
Gene Ontology:
Molecular function: dipeptidase activity; identical protein binding; protein binding; para-aminobenzoyl-glutamate hydrolase activity; hydrolase activity
Biological process: proteolysis; regulation of protein metabolic process; folic acid catabolic process
Cellular component: nucleoplasm; cytoplasm
Genetic constraint (gnomAD): Loss-of-function variants: 28 observed, 31.9 expected, observed/expected ratio (o/e) 0.88, 90% interval 0.65 to 1.2. The synonymous counts are far from expectation, so gnomAD's model fits this gene poorly and the ratio says little. Missense variants: 515 observed, 468.63 expected, observed/expected ratio (o/e) 1.1, 90% interval 1.02 to 1.18. Synonymous variants: 238 observed, 182.46 expected, observed/expected ratio (o/e) 1.3, 90% interval 1.17 to 1.45.
Homologues: Orthologues: chimpanzee PM20D2 (99% identical), rabbit PM20D2 (90% identical), dog PM20D2 (88% identical), pig PM20D2 (88% identical), rat Pm20d2 (82% identical), mouse Pm20d2 (81% identical), guinea pig PM20D2 (78% identical), macaque PM20D2 (73% identical), tropical clawed frog pm20d2 (69% identical).
Diseases named in the same sentence as PM20D2 in open-access papers:
PM20D2 is named in the same sentence as 1 disease in open-access papers, as found by Europe PMC text mining. Sharing a sentence is not in itself a finding about the gene and the disease. The quoted sentences say what the papers report.
prostate carcinoma (1 paper, 2017). A carcinoma that arises from epithelial cells of the prostate gland. "Our data suggest that also ORC3 and PM20D2 may represent CYCLOPS genes that could potentially serve as future drug targets in prostate cancers harboring large 6q deletions." (PMID 29312579, 2017).